ATP2B1-AS1 (ATP2B1 antisense RNA 1)
Synonyms: LINC00936
Gene: Long non-coding RNA gene on chromosome 12 (89,708,177 to 90,143,524, forward strand). Ensembl gene ENSG00000271614.
Diseases named in the same sentence as ATP2B1-AS1 in open-access papers:
ATP2B1-AS1 is named in the same sentence as 6 diseases in open-access papers, as found by Europe PMC text mining. Sharing a sentence is not in itself a finding about the gene and the disease.
ATP2B1-AS1 shares sentences with these, for which no sentence is quoted: acute myocardial infarction (2 papers); ovarian carcinoma (2); endometrial carcinoma (1); gastric cancer (1); lung adenocarcinoma (1); tumor (1).